MPPED1 (metallophosphoesterase domain containing 1)
Description:
May have metallophosphoesterase activity (in vitro).
Synonyms: 239AB; C22orf1; FAM1A
Tractability: PROTAC: its protein half-life has been measured.
Gene: Protein-coding gene on chromosome 22 (43,411,196 to 43,507,850, forward strand). Ensembl gene ENSG00000186732.
Gene Ontology:
Molecular function: cyclic-nucleotide phosphodiesterase activity; hydrolase activity
Genetic constraint (gnomAD): Loss-of-function variants: 16 observed, 34.63 expected, observed/expected ratio (o/e) 0.46, 90% interval 0.31 to 0.7. The upper end of that interval is the gene's LOEUF score, 0.7, which puts it in group 2 of 6, group 1 being the genes least tolerant of losing a copy. Missense variants: 307 observed, 467.38 expected, observed/expected ratio (o/e) 0.66, 90% interval 0.6 to 0.72. Synonymous variants: 199 observed, 198.94 expected, observed/expected ratio (o/e) 1, 90% interval 0.89 to 1.12.
Homologues: Orthologues: dog MPPED1 (99% identical), guinea pig MPPED1 (99% identical), pig MPPED1 (99% identical), rat Mpped1 (98% identical), mouse Mpped1 (98% identical), tropical clawed frog mpped1 (87% identical), macaque MPPED1 (83% identical), zebrafish mpped1 (80% identical), Drosophila melanogaster CG16717 (42% identical), Caenorhabditis elegans T07D4.2 (41% identical), Caenorhabditis elegans C25E10.12 (36% identical), Caenorhabditis elegans K07C11.7 (33% identical). Paralogues in human: MPPED2 (71% identical).
Diseases named in the same sentence as MPPED1 in open-access papers:
MPPED1 is named in the same sentence as 5 diseases in open-access papers, as found by Europe PMC text mining. Sharing a sentence is not in itself a finding about the gene and the disease. The quoted sentences say what the papers report.
prostate enlargement (1 paper, 2025). "A UK Biobank‐based GWAS confirmed an increased OR for SNPs at PGR (OR 1.36), whilst additionally revealing two SNPs protective against prostate enlargement symptomatology, nearby other genes including MPPED1 and NPAP1 (OR 0.72 and 0.66, respectively)." (PMID 39187949, 2025).
tumor (3 papers, 2020 to 2024). "Additionally, voltage-gated ion channels and genes like KCNQ5, KCNV1, ADAMTS14, MPPED1, and SLC24A2 are linked to tumor traits in these tumors." (PMID 39139281, 2024). "Importantly, we confirmed the negative correlation of the spatial TNOD marker MPPED1 and the spatial TINF marker KRT6A expression at the tumor-stroma interface by RNA FISH." (PMID 35986012, 2022).
MPPED1 also shares sentences with these, for which no sentence is quoted: cognitive decline (1 paper); Colon Cancer (1); somatotropinoma (1).